APC (APC regulator of Wnt signaling pathway)
Diseases named in the same sentence as APC in open-access papers (continued):
Sharing a sentence is not in itself a finding about the gene and the disease.
cancer (continued). "Mutations in APC have been found in several cancers, including colorectal, pancreatic, and hepatocellular, but they are reported to be much rarer in breast cancer." (PMID 27028212, 2016). "Beta catenin stability is known to be regulated by a cytoplasmic complex containing GSK3, axin, and APC; disruption of this complex is linked to progression of cancers of the colon and other organs." (PMID 26930581, 2016). "As the APC/C complex is also regulated by PTMs, we propose that infrequent cancer mutations in PTM sites drive tumors by deregulating the structure and function of the complex and impacting cell proliferation pathways." (PMID 27175787, 2016). "Nuclear APC staining of high intensity was associated with a significantly worse cancer-specific survival and increased overall recurrence rate compared to tumors with weak staining." (PMID 27577083, 2016). "The fact that of the 10 rarely mutated genes, 5 (BCL2L1, CDC42, DDX5, AKT1 and APC) are listed in cancer gene databases indicates such association-based selection is useful." (PMID 27808240, 2016). "In the laboratory, cross-mating of COX-2 knockout mice with MIN mice, which have mutation in the adenomatous polyposis coli (APC) gene, resulted in mice with significantly reduced formation of intestinal adenomas and cancers associated with APC mutation." (PMID 27074568, 2016). "Second, there is evidence that inhibition of the extracellular Wnt ligand-receptor interaction is effective in reducing tumorigenicity in cancers that harbor APC mutations." (PMID 27598201, 2016). "If these cancers were arising though the canonical mechanism of tumorigenesis, loss of APC would be expected, thus these tumors are developing through a non-canonical mechanism." (PMID 26863299, 2016). "Although many different kinds of mutation including β-catenin and APC have been found in Wnt pathways from different cancer types, in TCC, epigenetic silencing of Wnt antagonists appear to be more common." (PMID 27472396, 2016). "This is commonly due to mutation of the APC gene which is uncommonly mutated in BRAF mutant serrated pathway cancers." (PMID 27661107, 2016). "Using a cDNA array and after validation with a published dataset, we have also presented additional evidence for a role of APC in prostate cancer, namely that downregulated APC gene expression was associated with more aggressive cancer and a poor prognosis." (PMID 27898031, 2016). "The somatic APC (p.R790*) mutation has also been previously reported in the Catalogue Of Somatic Mutations In Cancer (COSMIC) database." (PMID 27799065, 2016). "A strong association of Wnt signaling in human cancer was identified when a correlation was noted between mutations of the β-catenin regulatory protein APC and familial adenomatous polyposis, which confers a greatly increased incidence of colorectal cancer." (PMID 27589803, 2016). "Our results confirmed that the cfDNA level and methylation of CpG islands of RASSF1A, FHIT, and APC genes in blood plasma can be used as noninvasive diagnostic markers of cancer." (PMID 27725787, 2016). "Mutations inactivating the APC tumor suppressor gene are believed to be critical in the majority of colon adenomas and carcinomas." (PMID 27578919, 2016).
cancer (continued). "Deregulated Wnt signaling plays roles in several cancers; most strikingly, mutations in Adenomatous polyposis coli (APC), a key negative regulator of Wnt signaling, initiate ∼80% of colon cancers." (PMID 26393419, 2015). "CRC is unusual compared to other cancers in that loss of function mutations in APC are much more frequent than activating mutations in β-catenin (i.e. in exon 3), ∼75% compared to ∼5%, respectively." (PMID 26240067, 2015). "Cancer associated mutations in APC, thus lead to an excessive accumulation of β-catenin and the concomitant expression of Wnt/β-catenin targeting genes, which together play important roles in colorectal tumorigenesis and metastasis." (PMID 26445050, 2015). "Canonical Wnt signaling can be constitutively activated in cancer by a variety of mechanisms including mutations in adenomatous polyposis coli (APC), Axin, and β-catenin." (PMID 26384318, 2015). "While the majority of these lines have mutations in APC, only two lines have β-catenin mutations according to the Cancer Cell Line Encyclopedia (CCLE)." (PMID 26134786, 2015). "We describe here a new and representative model for both familial and sporadic cancers associated with mutations in the APC tumor suppressor gene." (PMID 26097888, 2015). "In these more often APC-wild-type cancers, inhibition of DDX3 causes a potent reduction of Wnt signaling and a G1 arrest." (PMID 26311743, 2015). "Most cancer-linked APC mutations occur in the central region of APC and result in truncation of almost half of the C terminal regions of the protein." (PMID 25050571, 2014). "The variants found in four of the cancer genes APC, BRCA1, RET, and SDHB in our AJ centenarian sample had also been labeled as “almost certainly benign” in another sequencing study (ClinSeq) of 572 middle aged participants (17% of which are of AJ ancestry)." (PMID 25333069, 2014). "Our data directly support the previous model that the perfect [A8/T8] allele creates a hypermutable region within the APC gene, leading to cancer predisposition." (PMID 25033203, 2014). "Feeding a western diet of high fat content and low levels of calcium and vitamin D to APC knock-out mice resulted in a higher risk of cancer in the CIN pathway." (PMID 25356998, 2014). "While mutations in the Wnt/β-catenin pathway are responsible for certain types of cancers, most notably APC mutations in colorectal cancer, many cancers driven by overstimulation of this signaling do not harbor mutations in its components." (PMID 26056595, 2014). "Cancer-associated APC mutations primarily comprise premature stop-codons that lead to the expression of a truncated form of the protein that lacks Axin1 interaction motifs." (PMID 25392450, 2014). "Next, we used SW480 and RWP-1 cancer cells which carry APC-mutations and show constitutive WNT pathway activation." (PMID 24930890, 2014). "In some human cancers, mutation of either the APC gene or the β-catenin gene itself leads to the accumulation of β-catenin within the cancer cells." (PMID 25029906, 2014). "We demonstrate that naturally occurring cancer-causing APC (adenomatous polyposis coli) nonsense mutants which escape nonsense-mediated mRNA decay (NMD) are repressed by miRNA-mediated surveillance." (PMID 25107276, 2014). "APCMIN/+ mice have a single defective allele of APC and sporadically develop intestinal adenomas and early carcinomas." (PMID 24866282, 2014).
cancer (continued). "Inhibition of is predicted to limit sequestration of away from Axin and Axin-associated kinases and thereby to lower levels in cancer cells expressing truncated APC." (PMID 24086117, 2013). "To better understand the mechanisms leading to colorectal cancer after APC loss, we have used a mouse model in which we deleted Apc in the bowel and which developed several characteristics of early stage cancers." (PMID 23935526, 2013). "Colorectal cancer is most commonly associated with a mutation in adenomatous polyposis coli (APC) gene and is the second leading cause of deaths due to cancer in the United States." (PMID 23589074, 2013). "Genes encoding components of the destruction complex, for example APC or Axin, are often mutated, resulting in β-catenin accumulation in cancer samples." (PMID 23592547, 2013). "Curiously, the replication process appears to involve DNA copying by the error-prone DNA polymerase β insofar as about half of cancer-initiating APC point mutation hotspots sampled are attributable to errors of DNA polymerase β copying undamaged DNA in vitro." (PMID 24195059, 2013). "Full-length APC(1–2843) and cancer-associated, truncated APC proteins, APC(1–1638) and APC(1–1311) were produced in Sf9 insect cells." (PMID 24156781, 2013). "Dysplastic aberrant crypt foci can harbor mutations in APC, inactivation of which leads to activation of the Wnt pathway, a common mechanism for initiating polyp to cancer progression sequence." (PMID 24216997, 2013). "Hypermethylation at APC locus has been shown to be associated with cancer progression and the Gleason score." (PMID 23431474, 2013). "Mutations in the APC tumour suppressor gene represent the main initiating and rate-limiting event in the adenoma-carcinoma sequence leading to colon cancer in man." (PMID 24069241, 2013). "Loss of cellular adhesion junctions is known to be one of the key hallmarks of cancer invasion and metastasis, so it is unsurprising that mutations in β-catenin, Axin and APC have all been detected in human cancer." (PMID 22363759, 2012). "For example, aberrant alternative splicing of certain tumor suppressors, such as breast cancer 1 and 2 (BRCA1/2), Wilms tumor 1 (WT1), and adenomatous polyposis coli (APC), results in mutations that account for inherited and sporadic susceptibility to cancer." (PMID 23236423, 2012). "Most common mutations occur in the APC or β-catenin gene, which ultimately results in stabilization and nuclear accumulation of β-catenin in cancer cells." (PMID 22651859, 2012). "When spontaneous mutations occur that means APC cannot play a normal physiological function, the individual is at a higher risk of cancers, including colorectal cancer." (PMID 22514598, 2012). "Insight in the underlying molecular events will be invaluable in the development of novel strategies to counter dysregulated Wnt signaling by APC mutations in cancer." (PMID 21859464, 2011). "In the present study, we investigate the possibility of extending this approach to cancer linked to a nonsense mutation in APC gene." (PMID 21909382, 2011). "A large number of germline and somatic missense mutations in APC however link to various forms of cancer and are identified in a scattered pattern throughout the APC protein." (PMID 21859464, 2011). "Oxygen is further shown to be associated with genomic instability in two additional cancer models involving the APC tumor suppressor gene and chemical carcinogenesis." (PMID 21589870, 2011). "The tumors that arise in these mice resemble metaplastic carcinomas of the breast in humans, cancers previously associated with APC down-regulation." (PMID 22216254, 2011). "Mutations in APC, a negative regulator of the Wnt/ß-catenin pathway, can cause cancer as well as profound developmental defects." (PMID 22136118, 2011).
cancer (continued). "Constitutive β-catenin signaling, due to inactivating mutations in APC oractivating mutations within β-catenin itself, plays a critical role in thedevelopment of certain cancers." (PMID 21317452, 2010). "The doubling of FAP crypt stem cells increases the risk of cancer, and this addition effect of certain APC mutations along with one fewer rate-limiting k mutations better fits the observed incidence of FAP cancer with aging." (PMID 20051132, 2010). "In many cancers, activation of the Wnt/β-catenin pathway is associated with mutations of APC and β-catenin, with exon 15 of APC and exon 3 of β-catenin the most common mutation sites." (PMID 20302655, 2010). "More than 80% of colonic adenomas and carcinomas have mutations in Adenomatous polyposis coli (APC) gene, and loss of APC function results in constitutive activation of Wnt signaling." (PMID 20828404, 2010). "The majority of colorectal cancers are caused by mutations in the APC (adenomatous polyposis coli) gene, which is considered to be the earliest genetic defect in the aberrant crypt foci-adenoma-carcinoma sequence." (PMID 27713322, 2010). "Many of these genes, including INK4a, RASSF1a and APC, exhibit tumour suppressor functions whose inactivation associated with hypermethylation of CpG islands in 5′ regulatory regions occurs during cancer development." (PMID 19002169, 2009). "Loss of function of the SCF or APC pathways is involved in the initiation or progression of human cancer." (PMID 19302711, 2009). "In cancer, frequently mutations arise that lead to disruption of adherens junctions, such as loss of APC, loss of E-cadherin or mutationally activated β-catenin." (PMID 19924305, 2009). "APC mutation analysis of the mutation cluster region showed somatic mutations in 5/36 (14%) carcinomas; four were MUTYH associated transversions (G>T's); two were C>T transitions, one of them occurring together with a G>A transition (patient 6)." (PMID 19527492, 2009). "In colorectal cancer (CRC), mutations in APC, axin, or β-catenin itself promote β-catenin stabilization and transcription of target genes encoding cancer-associated proteins." (PMID 17897439, 2007). "The inappropriate activation of Wnt signalling through mutation of β-catenin or APC and/or downregulation of negative regulators such as SFRPs occurs frequently in cancers." (PMID 17848950, 2007). "De-regulation of the wingless and integration site growth factor (WNT) signaling pathway via mutations in APC and Axin, proteins that target β-catenin for destruction, have been linked to various types of human cancer." (PMID 17897439, 2007). "The specific detection of APC is of paramount importance due to its central role as a tumour suppressor protein, and its ability to result in the development of carcinomas when mutated." (PMID 17595655, 2007). "The Wnt signaling pathway is activated by mutations in the APC and β-catenin genes in many types of human cancer." (PMID 17020613, 2006). "We conclude that early age at diagnosis and family history of cancer cannot be used to predict who is likely to harbour the I1307K APC germline mutation carriers." (PMID 11720476, 2001). "Some clinical investigations showed that tankyrase inhibitors might be promising anti-cancer agents, especially for APC-mutated CRC." (PMID 40943055, 2025). "Loss of APC allows β-catenin to translocate to the nucleus, bind to the PD-L1 promoter, leading to increased transcription of PD-L1 and its protein expression on cancer cells, thus, inhibiting tumor specific immunity." (PMID 39944699, 2025). "An identical cancer pathway may be associated with multistep carcinogenesis, accompanied by APC mutations in mutation hotspots." (PMID 41488735, 2025). "Although clinical interventions are primarily determined by phenotype in FAP, specific APC gene variants may inform risk prediction for cancer or desmoid disease." (PMID 40192835, 2025).
cancer (continued). "However, when APC functions abnormally, the accumulation of β-catenin triggers the transcription of Wnt target genes associated with cancer cell proliferation, survival, and metastasis, thereby creating an immunosuppressive TME." (PMID 40429703, 2025). "Additionally, flavonoids like silibinin selectively inhibit WNT signaling in cancer cells harboring specific mutations (e.g., mutant APC), highlighting their potential for targeted therapeutic strategies." (PMID 40874062, 2025). "In addition, studies are needed to determine the efficacy of JPI-547 in various cancers harboring different genetic aberrations, such as R-spondin fusions and APC mutations, that confer Wnt pathway dependency." (PMID 40959288, 2025). "In APC-deficient cancers, β-catenin accumulates due to its impaired degradation." (PMID 40136551, 2025). "In cancer, mutations in APC or CTNNB1 (β-catenin) lead to permissive β-catenin machinery, subverting TCF/LEF transcription factors to unleash tumorigenic gene expression, including MYC, CCND1, and AXIN2, promoting unbridled proliferation, stemness, and therapeutic resistance." (PMID 40874062, 2025). "The differences observed in the mutation rates of WNT/APC/β-catenin pathway components in the two groups differing in SOX2 expression was in a significant degree due to the high mutation rate in MSI-high cancers, which were more prevalent in cancers with suppressed SOX2 mRNA expression." (PMID 40149431, 2025). "Further observation of the patient and her family may elucidate the role of the APC variant in the personal history of cancer." (PMID 39684352, 2024). "In addition, alterations in MAP2K4, FGFR3, and APC genes have been linked to cancer progression and treatment." (PMID 39031010, 2024). "When there is an APC mutation, β-Catenin builds up, moves to the nucleus, and promotes the transcription of Wnt target genes in gastrointestinal epithelial stem cells, which can lead to cancer." (PMID 39554609, 2024). "Additionally, patients with a germline APC mutation at codon 1,309 are known to be at increased risk of cancer in the rectal remnant." (PMID 38555871, 2024). "Only a small number of patients with pediatric cancer have germline or genetic mutations, mainly in APC or β-catenin, respectively, suggesting that mutation-independent mechanisms are involved in the development of HBL, HCN-NOS and perhaps pediatric HCC as well." (PMID 39001363, 2024). "Importantly, c-MYC is the master gene responsible for the oncogenic activity of the Wnt/β-catenin pathway in the intestine, where APC mutations are sufficient for cancer initiation." (PMID 39065798, 2024). "Therefore, impairing APC/C function represents an opportunity for the treatment of cancer and malignancies associated with SAC dysregulation." (PMID 39595615, 2024). "Moreover, we demonstrate that the centrosome loss-induced growth defect/death of the APC-mutant cancer colorectal organoids tested is mediated by β-catenin, the downstream effector of the canonical WNT pathway." (PMID 38324534, 2024). "The percentage of APC mutations was 25.3% in MSI cancers and 20.4% in MSS cancers." (PMID 36879264, 2023).